GK-IT1 (GK intronic transcript 1)
Gene: Long non-coding RNA gene on chromosome X (30,671,635 to 30,672,166, forward strand). Ensembl gene ENSG00000229331.
Diseases named in the same sentence as GK-IT1 in open-access papers:
GK-IT1 is named in the same sentence as 1 disease in open-access papers, as found by Europe PMC text mining. Sharing a sentence is not in itself a finding about the gene and the disease. The quoted sentences say what the papers report.
cancer (1 paper, 2022). A tumor composed of atypical neoplastic, often pleomorphic cells that invade other tissues. "The expression of GK intronic transcript 1 (GK‐IT1) was analyzed using ESCC RNA‐seq data from The Cancer Genome Atlas database." (PMID 35608100, 2022).